KIF2A (kinesin family member 2A)
Diseases named in the same sentence as KIF2A in open-access papers (continued):
Sharing a sentence is not in itself a finding about the gene and the disease.
tumor (25 papers, 2014 to 2026). "A larger study of NSCLC patients found that high KIF2A protein expression was associated with increased pathological tumour grade and size, the presence of lymph node metastasis, and worse disease-free and overall survival." (PMID 40002279, 2025). "Our study found that tumor KIF2A high was associated with poor accumulating OS in GC patients, which was similar to the findings of a previous study." (PMID 35313389, 2022). "After adjustment via multivariate Cox's regression, tumor KIF2A high expression independently linked with worse disease‐free survival (p = 0.033)." (PMID 35313389, 2022). "In our study, we found that increased KIF2A expression was associated with larger tumor size, more advanced N stage and TNM stage." (PMID 35313389, 2022). "In conclusion, KIF2A is highly expressed and its elevated expression associates with larger tumor size, advanced N stage, TNM stage as well as poor survival in GC patients; meanwhile, its knockdown enhances the chemosensitivity to oxaliplatin and capecitabine in GC cell lines." (PMID 35313389, 2022). "Tumor KIF2A high expression was associated with poor accumulating OS (p = 0.037)." (PMID 35313389, 2022). "Moreover, tumor KIF2A high expression was associated with poor overall survival; meanwhile, KIF2A expression (high vs. low) independently associated with shorter DFS." (PMID 35313389, 2022). "For instance, high KIF2A expression was correlated with tumour stage and lymph node metastasis in a cohort of LUAD tumours." (PMID 40002279, 2025). "Parallel observations in the circRNA combination cohort revealed sustained downregulation of key classical oncogenes (PIK3CA) and novel tumor-associated genes (ANXA2, KIF2A, NCAPG2, PAIP1)." (PMID 40426998, 2025). "The results discovered that compared with adjacent tissues, the staining intensity of KIF2A showed marked elevation in tumor tissues." (PMID 38433242, 2024). "By suppressing membrane-type 1-matrix metalloproteinase, KIF2A knockdown in gastrointestinal cancers decreases tumor cell invasion." (PMID 36793588, 2023). "A total of 160 surgical GC patients were reviewed, with their tumor and adjacent tissues acquired for immunohistochemical (IHC) assay to measure KIF2A expression, then scored by a semi‐quantitative method (IHC score: 0–12)." (PMID 35313389, 2022). "We also observed that the levels of KIF2A mRNA and protein were apparently decreased in mice tumor tissues of the sh-circ_IRAK3 group." (PMID 35164763, 2022). "Kinesin family member 2A reflects larger tumor size, advanced TNM stage, improved chemosensitivity, and predicts unfavorable survival in GC." (PMID 35313389, 2022). "Meanwhile, KIF2A IHC score was increased in the tumor tissue (5.6 ± 3.1) than in the adjacent tissue (2.9 ± 1.7) (p < 0.001); KIF2A high percentage (defined as KIF2A IHC score >3) was also higher in tumor tissue than in adjacent tissue (p < 0.001)." (PMID 35313389, 2022). "The results showed that KIF2A expression was increased in the tumor tissue than in the adjacent tissue." (PMID 35313389, 2022). "The expression level of KIF2A in tumor tissues is positively correlated with lymph node metastasis and FIGO (Federation International of Gynecology and Obstetrics) staging, and is closely related to disease-free survival and overall survival of the patients." (PMID 36447525, 2022). "Kinesin family member 2A expression was elevated in the tumor tissue compared to the adjacent tissue (IHC score: 5.6 ± 3.1 vs. 2.9 ± 1.7, p < 0.001)." (PMID 35313389, 2022). "Elevated KIF2A IHC score was correlated with tumor size≥3 cm (p = 0.014), more advanced N stage (p = 0.004) and TNM stage (p = 0.011)." (PMID 35313389, 2022). "In line with previous studies, our study discovered that KIF2A expression was elevated in the tumor tissue than in the adjacent tissue in GC patients." (PMID 35313389, 2022).
tumor (continued). "Some studies believe that the expression of KIF2A increases the dynamic instability of MTs, thereby supporting tumor cell migration and invasion." (PMID 36447525, 2022). "Our findings also confirmed that downregulating KIF2A expression decreased tumor cell viability, accompanied by downregulation of pAKT levels." (PMID 28616658, 2017). "Our findings were also consistent with a previous study which showed that blocking KIF2A induced a decrease in tumor cell viability, accompanied by downregulation of pAKT levels." (PMID 28616658, 2017). "High expression of KIF2A correlated significantly with the patient's age (p = 0.021), tumor histology (p = 0.039), TNM stage (p = 0.008), and lymph node metastasis (p = 0.009)." (PMID 27773961, 2016). "We explored KIF2A expression by performing IHC analysis on TMAs comprising 461 GC and 65 matched tumor adjacent tissues from patients with GC." (PMID 27773961, 2016). "IHC analysis of TMA sections showed that KIF2A was expressed mainly in the tumor epithelial cells, and staining showed that it occurred primarily in the cytoplasm." (PMID 27773961, 2016). "KIF2A induces tumor cell proliferation by regulating the PI3K/Akt pathway." (PMID 36793588, 2023). "Besides, tumor KIF2A expression was related to larger tumor size (p = 0.014), higher N stage (p = 0.004) and TNM stage (p = 0.011); however, it was not linked with other clinicopathological features (all p > 0.05)." (PMID 35313389, 2022). "Signally, tumor KIF2A high expression predicted poor overall survival (p = 0.037)." (PMID 35313389, 2022). "Kinesin family member 2A expression was detected by IHC assay in tumor and adjacent tissue." (PMID 35313389, 2022). "Besides, tumor KIF2A expression was correlated with larger tumor size, higher N stage and TNM stage." (PMID 35313389, 2022). "KIF2A has been reported to be upregulated in many tumor tissues." (PMID 35164763, 2022). "Based on these implications about the tumor-promotive effect of KIF2A in various cancers, we speculated that KIF2A might also play a crucial role in disease progression and underlying mechanisms of AML, whereas relevant evidence is rarely reported." (PMID 33331418, 2020). "Therefore, KIF2A is involved in tumor growth, metastasis, and invasion, and confers chemoresistance in various human tumors." (PMID 28616658, 2017). "Collectively, these findings suggest that KIF2A might promote tumor growth and invasion partially through stimulating the PI3K/AKT signaling pathway." (PMID 27773961, 2016). "Therefore, KIF2A expression was elevated in tumor tissue than in adjacent tissue." (PMID 35313389, 2022). "Furthermore, NETO1 depletion inhibits the ability of KIF2A to promote tumour progression." (PMID 32638511, 2020). "Silencing the KIF2A gene suppressed the proliferation of squamous cell carcinoma of the tongue (SCCT, cell line Tca8113) and synergized the tumor suppression effect of 5-fluorouracil in a nude-mice model." (PMID 27773961, 2016). "We found that simultaneously high KIF2A and HER2-neu expression were significantly related to FIGO stages (P < 0.001), metastasis (P = 0.030), tumor type (P = 0.014), and level of CA-125 (P = 0.033)." (PMID 26937910, 2016). "Following this second hypothesis, we computationally found reliable interactions between UCA1 and the 3′-UTRs of ANLN, BIRC5, IPO7, KIF2A, and KIF23 that overlapped several miRNA-binding sites of tumor-suppressor miRNAs." (PMID 30195762, 2018). "High KIF2A expression, serum LDH level, and IPI score maintained their prognostic value in multivariate analyses, indicating that dysregulation of KIF2A may be related to tumor progression in DLBCL." (PMID 28616658, 2017). "KIF2A is overexpressed in NSCLC cell lines compared to non-malignant lines and protein expression is upregulated in NSCLC tumours relative to non-malignant tissues." (PMID 40002279, 2025).
cancer (19 papers, 2014 to 2025). A tumor composed of atypical neoplastic, often pleomorphic cells that invade other tissues. "The abnormal expression and dysfunction of KIF2A are associated with tumorigenesis and the progression of certain types of human cancers." (PMID 27773961, 2016). "We lacked in vitro data to verify our results and although we did examine the function of KIF2A in the GC cell lines, further studies are necessary to investigate the underlying mechanisms by which KIF2A influences the invasion and metastasis of cancer cells." (PMID 27773961, 2016). "Moreover, among LUSQ patients with early clinical stage (stage I and II), high expression of KIF2A was significantly associated not only with prognosis but also with cancer recurrence." (PMID 30813343, 2019). "Interestingly, several lines of evidence have indicated that KIF2A might be implicated in carcinogenesis and the development of drug resistance in cancer cells." (PMID 27773961, 2016). "Our current data confirmed that aberrant expression of KIF2A enhanced cancer cell aggressiveness in LUSQ cells." (PMID 30813343, 2019). "Cancer cell proliferation was significantly suppressed by si-KIF2A transfection in comparison with those in mock- or control-transfected LUSQ cells." (PMID 30813343, 2019). "Further analyses showed that cancer cell motility, including migration and invasive abilities, was markedly inhibited by knockdown of KIF2A via si-KIF2A transfection compared with those in mock- or control-transfected LUSQ cells." (PMID 30813343, 2019). "The results of 9 studies involving 1839 cancer patients demonstrated that high KIF2A expression was significantly related to a shorter OS (HR = 2.23, 95% CI = 1.87–2.65, P < .001)." (PMID 31725680, 2019). "Although few investigations have explored the role of KIF2A in cancers, there are some published findings in accordance with our results." (PMID 27773961, 2016). "The formation of monopolar spindles and inhibition of cellular proliferation were also observed in human cancer cells treated with anti-KIF2A siRNA or Xenopus eggs with a KIF2A antibody." (PMID 24950762, 2014). "The KIF2A expression level in primary cancer tissues was higher than that in the adjacent epithelial tissue, with mean scores at 7.1 ± 0.7 vs. 6.3 ± 1.0 (P < 0.05)." (PMID 24950762, 2014). "Our current study demonstrated a relationship between HER2 and KIF2A expression in cancer cells (P < 0.05), which needs further investigation." (PMID 24950762, 2014). "Kinesin family member 2a (KIF2A), a type of motor protein found in eukaryotic cells, is associated with development and progression of various human cancers." (PMID 24950762, 2014). "The proliferation, migration and invasion of cancer cells in vitro were suppressed by KIF2A gene silencing (P < 0.05)." (PMID 24950762, 2014). "The expression of KIF2A in cancer tissues was higher than that in normal adjacent tissues from the same patient (P < 0.05)." (PMID 24950762, 2014). "However, miR-206 targets KIF2A, resulting in the inhibition of cancer cell proliferation, migration, invasion, and induction of apoptosis." (PMID 38793064, 2024). "As an MT depolymerization protein, KIF2A plays a role in cancer progression." (PMID 36447525, 2022). "Kinesin family member 2A (KIF2A) plays an important role in cancer progression." (PMID 35071748, 2022). "Additionally, previous studies have already reported the correlation between KIF2A inactivation and induced apoptosis in cancer cells." (PMID 34404749, 2021). "The expression level of KIF2A in exosomes could be lower in the cancer group than in the normal group if tumors absorbed KIF2A required for cell mitosis and proliferation." (PMID 34827689, 2021). "A better understanding on the effect of KIF2A in cancer cells may contribute to explore novel treatment targets." (PMID 33331418, 2020). "Some previous studies have revealed the predictive value of KIF2A in various cancers." (PMID 33331418, 2020).
cancer (continued). "Recently, the influence of KIF2A on cancer cells has been investigated." (PMID 33331418, 2020). "Moreover, the correlation of KIF2A expression with clinical characteristics in cancers is also observed." (PMID 33331418, 2020). "Overall, high expression of KIF2A and KIF20A was associated with shorter OS, and these two KIF members can serve as independent factors for predicting the survival outcomes of patients with cancer." (PMID 31725680, 2019). "Furthermore, it was demonstrated that patients with a high expression of KIF2A tend to have a poor prognosis for certain types of human cancers." (PMID 27773961, 2016). "According to recent studies, KIF2A is present throughout the cell and might accelerate MT turnover, resulting in an increase in cancer cell motility." (PMID 27773961, 2016). "Despite its close relationship with MCAK and functions on the mitotic spindle, KIF2A increases the migration rate of cancer cells via the AKT serine/threonine kinase 1 signaling, independent of its depolymerase activity, which could not be verified in MCAK overexpressing cells." (PMID 34830827, 2021). "By elucidating the structural basis for Kif2A-induced WIN-S7 pocket formation, we lay the groundwork for further exploration of the role of WDR5 in mitosis and cancer biology." (PMID 40302551, 2025). "The expression mechanisms of KIF2A and KIF20A are different and complicated in various types of cancer." (PMID 31725680, 2019). "Two well-known KIF members, KIF2A and KIF20A, were investigated to evaluate their potential values as novel prognostic biomarkers in human cancer." (PMID 31725680, 2019). "Kinesin family member 2A (KIF2A), a conserved motor protein, plays a critical role in the pathogenesis and prognosis of several malignant tumors." (PMID 28616658, 2017). "The combination of miRNA (miR-142-3p), mRNAs (CXCL5, KIF2A, RGS18, APL6IP5, and DAPP1), and snoRNAs (SNORD17, SCARNA12, SNORA6, SNORA12, SCRNA1, SNORD97, SNORD62, and SNORD38A) clearly distinguished the normal samples from the cancer group samples." (PMID 34827689, 2021). "Subgroup analysis of the pooled HR of OS with KIF2A and KIF20A expression in patients with cancer." (PMID 31725680, 2019). "Thus, further large-scale, high-quality, and better designed multi-center studies should be performed to clarify the function of KIF2A and KIF20A in various human cancers." (PMID 31725680, 2019). "Therefore, we performed this meta-analysis of eligible studies to further examine the prognostic significance of KIF2A and KIF20A in different types of human cancers." (PMID 31725680, 2019). "Knocking down either KIF2A or MCAK reduced the ability of KRASG12V-expressing transformed HBECs to migrate and invade, suggesting that aberrant expression of these proteins during transformation can contribute to the migratory potential of cancer cells." (PMID 27773961, 2016). "Kinesin family protein 2A (KIF2A), an M-type nonmotile microtubule depolymerase, has attracted attention for its role in carcinogenesis and poor prognoses in various human cancers." (PMID 27773961, 2016). "Third, the cut-off values, which were used to distinguish between high and low groups of KIF2A/KIF20A expression, were difficult to define by the uniform criteria because of the diversity of different cancer types, which may have led to some heterogeneity in the results." (PMID 31725680, 2019). "KIF2A expression in cancer tissue with lymph node metastasis and HER2 positive cancer were higher than that in cancer tissue without (P < 0.05)." (PMID 24950762, 2014).
infection (1 paper, 2017). The state of being infected such as from the introduction of a foreign agent such as serum, vaccine, antigenic substance or organism. "At 3 days after infection, knockdown of Kif2a significantly decreased the size of neurospheres compared to those derived from control cells, implying an effect of Kif2a on cell proliferation." (PMID 28591194, 2017).
KIF2A also shares sentences with these, for which no sentence is quoted: developmental delay (2 papers); Lung Squamous Cell Carcinoma (2); neurodevelopmental disorder (2); airway hyperresponsiveness (1); breast tumor (1); congenital hydrocephalus (1); embryonal carcinoma (1); epileptic seizures (1); glioblastoma (1); infantile spasms (1); Intellectual disability (1); intraepithelial neoplasia (1); learning disabilities (1); liver cancer (1); metastasis (1); nasopharyngeal carcinoma (1); neurological disorders (1); non-small cell lung carcinoma (1); Nystagmus (1); pancreatic cancer (1); preeclampsia (1); renal papillary cell carcinoma (1); schizophrenia (1).